IL6 (interleukin 6)
Diseases named in the same sentence as IL6 in open-access papers (continued):
Sharing a sentence is not in itself a finding about the gene and the disease.
Stroke (continued). "Specifically, it has been indicated that stroke patients had significantly higher levels of pro-inflammatory IL-6 compared to controls, 12 hours after stroke onset." (PMID 40364646, 2026). "The model explicitly incorporates nonlinear feedback (IL-10 suppression of TNF-α/IL-6), cross-activation (NF-κB-mediated TNF-α/IL-6 synergy), and empirical parameterization from clinical stroke data." (PMID 41557608, 2026). "These dynamics were captured under initial cytokine conditions of 0.1 nM (TNF-α), 0.05 nM (IL-6), and 0.01 nM (IL-10), using parameter values derived from stroke literature and cross-validated through simulation stability." (PMID 41557608, 2026). "This delay, driven by cumulative exposure to TNF-α/IL-6 and implemented via a Hill function with a transcriptional lag, mirrors reported kinetics in stroke patients and experimental models, where IL-10 peaks between 36–60 hours post-insult." (PMID 41557608, 2026). "So far, it has been shown that in stroke patients, higher levels of IL-6 in plasma correlate with increased stroke severity and poor long-term prognosis." (PMID 40305179, 2025). "At Day 1, the correlation between IL-6 and NIHSS was strong (p < 0.01), indicating that higher IL-6 levels were associated with higher stroke severity." (PMID 39859987, 2025). "This dysregulation led to hyperactivated T cells, higher levels of cytokines (IL-2, IL-6, IL-10, IFN-γ), and an increased risk of stroke." (PMID 41156185, 2025). "Gene expression profiling revealed an upregulation of proinflammatory cytokines (TNF-α, IL-1β, IL-6) and the anti-inflammatory cytokine IL-10, particularly during the first three days post-stroke." (PMID 41373607, 2025). "Mechanistically, IL‐6 mediated inflammation emerges as a key driver in CHIP‐related stroke pathogenesis." (PMID 40702735, 2025). "Neutrophils synthesize and secrete pro-inflammatory factors such as TNF-α, IL-1β, and IL-6 and promote the expression of MMP9, which aggravates cerebrovascular endothelial cell injury after stroke and increases the risk of hemorrhagic complications." (PMID 38740617, 2025). "Other studies have found that the levels of Th17-related cytokines, including IL-6, in serum, had minimal predictive value for the recovery of cognitive functions during subacute hospital rehabilitation after a stroke." (PMID 40305179, 2025). "It was also found that increased IL-6 expression indicates an inverse correlation with stroke severity, infarct size, short-term prognosis, and post-hospital improvement, assessed between discharge and 3 months." (PMID 40305179, 2025). "Specifically, PPARα KO led to increased expression levels of Gadd45b, Nppa, Hdc, Lcn2, Il6, Sox4, Marcksl1, Saa3, Ucn2, Met, Dusp10, Elovl7, Ngf, C3, Il11, Hmox1, Alox5, Tnfsf9, Angptl4, Plin2, H19, Csf2rb, Atf3, and Col7a1 following stroke." (PMID 40362325, 2025). "During ischemia, inflammatory mediators are released, among which IL-6 plays a particularly important role in the acute phase of a stroke." (PMID 40305179, 2025). "In our previous studies, we demonstrated the diagnostic potential of salivary tumor necrosis factor α (TNF-α), interleukin 6 (IL-6), interleukin 10 (IL-10) and xanthine oxidase (XO) in the differential diagnosis of stroke patients." (PMID 40520895, 2025). "In humans, high circulating levels of TNF‐α and IL‐6 within the first 12 h after stroke are positively correlated with stroke severity and an unfavorable prognosis of stroke patients." (PMID 40804606, 2025). "IL-6 levels can be useful as an analytical biomarker for stroke recurrence after AIS, and its concentration reflects ethnic differences." (PMID 40305179, 2025). "Key cytokines such as IL-6, IL-1β, TNF-α, and chemokines like IL-8 are rapidly released after stroke onset and are strongly associated with infarct size, neurological deterioration, and poor functional recovery." (PMID 40869247, 2025).
Stroke (continued). "Receiver operating characteristic (ROC) analysis was performed to assess the diagnostic accuracy of IL-6, TNF-alpha, and NIHSS at admission in predicting stroke outcomes." (PMID 39859987, 2025). "IL-6 is also one of the factors influencing demyelination and myelin regeneration following damage to the white matter integrity after a stroke." (PMID 40305179, 2025). "Local and systemic inflammatory responses, characterized by elevated levels of tumor necrosis factor-alpha (TNF-α) and interleukin-6 (IL-6), have been well-established in post-stroke patients." (PMID 39745590, 2025). "The worldwide STABILITY trial found that lower glomerular filtration rate (GFR) and higher interleukin-6 (IL-6) levels were signs of acute myocardial infarction (AMI), stroke, and death from any cause." (PMID 40027896, 2025). "Specifically, comparing the highest to the lowest quartile, IL-6 exhibited a risk ratio (RR) of 1.35 for MACE and 1.33 for recurrent stroke, while hsCRP showed an RR of 1.31 for MACE." (PMID 40217803, 2025). "In our previous study, we evaluated the diagnostic potential of unstimulated and stimulated saliva in assessing TNF-α, IL-6 and IL-10 in stroke patients." (PMID 40520895, 2025). "Pro-inflammatory factors secreted by neutrophils, such as TNF-α and IL-6, promote the expression of MMP-9, which exacerbates endothelial damage in cerebral vessels following stroke and increases the risk of hemorrhagic complications." (PMID 40697574, 2025). "Gene expression profiling showed upregulation of proinflammatory mediators (TNF-α, IL-1β, IL-6) and the anti-inflammatory cytokine IL-10, most prominently during the first three days post-stroke, with expression levels generally higher in older patients." (PMID 41373607, 2025). "In the GluN3A KO brain three days after stroke, inflammatory factors IL-1β, IL-6, IL-10, and/or TNFα were significantly elevated, while MEM largely prevented these increases." (PMID 41369361, 2025). "The visualization results indicate that in the XGBoost model, LDH, WBC, NIHSS, Aphasia, and IL-6 are the top 5 most important features affecting the degree of stroke recurrence." (PMID 40917676, 2025). "IL-6 levels rise relatively quickly after a stroke due to its role in the acute inflammatory response." (PMID 40142325, 2025). "Clinically, elevated serum levels of interleukin-1β (IL-1β), interleukin-6 (IL-6), and tumor necrosis factor-α (TNF-α) at hospital admission correlate with significantly higher PSD risk in stroke patients." (PMID 41164411, 2025). "Astrocytes, through IL-6 regulation, support neurovascular regeneration and functional recovery post-stroke." (PMID 40305179, 2025). "Proinflammatory intracellular signaling cascades and transcription factors, for example, NF-κB, ROS, MMPs, and the release of proinflammatory cytokines, especially IL-1β, IL-6, and TNF-α, are associated with BBB dysfunction after stroke." (PMID 40740844, 2025). "IL-6 levels measured upon admission have been shown to significantly correlate with both initial stroke severity and long-term functional status." (PMID 40869247, 2025). "By increasing angiogenesis, IL-6 enables neuronal regeneration and recovery of function during a stroke." (PMID 40305179, 2025). "Elevated levels of pro-inflammatory cytokines—particularly IL-1β and IL-6—have been detected up to three months post-stroke, with higher concentrations observed in patients who experienced larger strokes." (PMID 41003011, 2025). "During the acute phase of stroke, the inflammatory cytokine IL-6 increases substantially, worsening ischemic damage." (PMID 40526615, 2025). "The increase in the mRNA expression of one of the most important pro-inflammatory interleukins—IL6—was found 3 days after stroke induction compared to in the contralateral hemisphere (p < 0.01) and to day 7 (p < 0.01)." (PMID 40332314, 2025).
Stroke (continued). "Its ability to lower harmful mediators like IL-1β and IL-6 while enhancing protective factors such as IL-10 suggests a promising therapeutic strategy in stroke, traumatic brain injury, and subarachnoid hemorrhage." (PMID 40362194, 2025). "IL-1β has been detected within 1 h after ischemic brain injury, and IL-6 was increased within a few hours after onset of ischemia and up to 90 days after stroke." (PMID 40362186, 2025). "In humans, IL6 is a very important factor which serves as the marker of infarct size and post-stroke survival." (PMID 40332314, 2025). "Previous immune‐related therapeutic approaches for stroke focus on inhibiting pro‐inflammatory cytokines, such as IL‐6 or TNF‐α, which are involved in the inflammatory response and neuroinflammation post‐stroke." (PMID 40657554, 2025). "It has been shown that the increase in the acute phase immune response factor, stimulated by interleukin 6 (IL-6), can rise not only during the acute phase of stroke but also in response to a broad spectrum of systemic inflammatory conditions." (PMID 40305179, 2025). "For example, lipid nanoparticles containing siRNA targeting IL-6 dramatically reduced inflammatory indicators and neuronal death in stroke models." (PMID 39861166, 2025). "Several studies have confirmed these mechanisms and investigated stroke biomarkers, such as IL-6, S100B, NSE, D-Dimer and GFAP in T2DM populations, demonstrating their relevance to stroke risk." (PMID 41150802, 2025). "Conversely, during the recovery phase of stroke, IL-6 contributes to neuroprotection and facilitates ischemic brain tissue restoration." (PMID 40526615, 2025). "Emerging research implicates neuroinflammatory pathways in the pathogenesis of PSD, where post-stroke immune activation mediates elevated cerebral cytokine production (IL-1β, IL-6, TNF-α)." (PMID 41164411, 2025). "In summary, both IL-6 and CRP are inflammatory biomarkers with significant predictive value for the risk of recurrent vascular events after stroke." (PMID 40217803, 2025). "For example, dim light exposure following experimental stroke or global ischemia increased proinflammatory cytokines including TNFα, IL-6, and IL-1β31,32." (PMID 41256678, 2025). "IL-6 represents a complex therapeutic target, as it plays both a toxic, inflammatory role and a regenerative role in the pathophysiology of stroke." (PMID 40305179, 2025). "In stroke, IL-10 modulates the immune response by inhibiting the synthesis of pro-inflammatory cytokines (e.g., IL-1β, IL-6, TNF-α), suppressing antigen presentation, and downregulating adhesion molecules on endothelial cells." (PMID 40869247, 2025). "Immediately after the stroke, there is a rapid activation of the peripheral immune system characterized by upregulation of proinflammatory cytokines such as IL‐1β, IL‐6, TNF‐α, and IFN‐c, as well as chemokines, C‐C motif chemokine ligand (CXCL)‐1 and CXCL‐2." (PMID 40804606, 2025). "Pro-inflammatory cytokines like IL-1β, IL-2, and IL-6 are typically found at low levels in the brain, but their levels increase following a stroke." (PMID 40292265, 2025). "IL-6 plays a role in the acute phase of stroke as a mediator of the inflammatory process, a reliable prognostic factor, and a neurotrophic factor in the later stages of brain ischemia development." (PMID 40305179, 2025). "The role of IL6 varies between post-stroke phases; in the acute phase, IL6 has pro-inflammatory properties, whereas in the subacute and prolonged phase it acts as neurotrophic mediator." (PMID 40332314, 2025). "In a stroke model, it improved neurological outcomes by reducing microglial activation and the expression of IL-6, IL-1β, and TNF-α, likely through inhibition of NF-κB." (PMID 40430456, 2025). "Stroke induces the release of pro-inflammatory cytokines, such as interleukin-6 (IL-6), interleukin-1β (IL-1β), tumor necrosis factor-α (TNF-α), and interleukin-18 (IL-18), while reducing anti-inflammatory cytokines like IL-10 and IL-13." (PMID 40529498, 2025).
Stroke (continued). "As a potential biomarker and therapeutic target, IL-6 offers promising but complex insights into stroke treatment, requiring careful timing and understanding of its dual nature." (PMID 40142325, 2025). "In our study, only interleukin-6 (IL-6) showed a significant difference between stroke and non-stroke groups." (PMID 41362543, 2025). "During the post-stroke inflammatory cascade, cytokines such as interleukin-6 (IL-6) and tumor necrosis factor-α (TNF-α) are released, promoting oxidative stress and increasing erythrocyte membrane permeability." (PMID 40739542, 2025). "In the early phase of stroke, IL-6 is induced by IL-1β and TNF-α and amplifies the inflammatory cascade." (PMID 40869247, 2025). "An analysis of 8420 patients demonstrated that elevated baseline levels of IL-6 and hsCRP were independently correlated with a higher risk of major adverse cardiovascular events (MACE) and recurrent stroke." (PMID 40217803, 2025). "The increased expression of IL6 was observed three days after stroke onset in the hemisphere affected by the stroke." (PMID 40332314, 2025). "Particularly, elevated IL-6 and TNF-α levels have been independently associated with worse functional outcomes in stroke patients, even in the presence of technically successful thrombectomy." (PMID 41195016, 2025). "Carriers of pro-inflammatory alleles exhibit higher CRP and IL-6 levels when consuming high-DII diets and display greater susceptibility to stroke, implying a gene–diet interaction along the diet–inflammation–stroke axis." (PMID 40686813, 2025). "In the acute phase of stroke, high levels of IL6 can contribute to an inflammatory response by activating immune cells and promoting the release of other pro-inflammatory cytokines." (PMID 40362325, 2025). "A relatively stable concentration of IL6 in the blood serum was noticed before as well as after the stroke (46.14–85.67 pg/mL)." (PMID 40332314, 2025). "Other cytokines, such as the interleukin-1 (IL-1) and interleukin-6 (IL-6) families, also exhibit pleiotropic effects during stroke." (PMID 40943626, 2025). "Since IL-6 levels rise sharply in stroke patients soon after the ischemic event, it is a crucial inflammatory factor." (PMID 40142325, 2025). "Interleukin-6 plays an important role in modulating the inflammatory response of the nervous system in stroke." (PMID 40305179, 2025). "For example, plasma levels of IL-6 and lipoprotein-associated phospholipase A2 (Lp-PLA2) have been associated with an increased stroke risk in clinical studies." (PMID 40949500, 2025). "Elevated C-reactive protein (CRP) and interleukin 6 (IL-6) levels can signal inflammation, which plays a role in stroke development and progression." (PMID 41296388, 2025). "In a prospective cohort study, patients with TIAs within 7 days prior to stroke had lower blood levels of IL-6, supporting that ischemic preconditioning can reduce the systemic inflammatory response." (PMID 38317957, 2024). "The serum MPO-DNA, PAD4, C1q, IL-1β, IL-6 and IL-8 reach their peak at 24 hours after stroke onset and show a decreasing trend during acute phase." (PMID 39737165, 2024). "The inflammatory cytokines induced by this phenotype, including tumor necrosis factor-alpha (TNF-α), interleukin-1β (IL-1β), and interleukin-6 (IL-6), prolong the inflammatory response and exacerbate brain damage following stroke." (PMID 39639187, 2024). "Studies have shown that serum levels of IL-6, IL-5, IL-10, and IL-2 in stroke patients are closely correlated with stroke prognosis." (PMID 38742047, 2024). "The adverse effects of leukocytosis, elevated CRP levels, and other inflammatory markers, such as IL-6, on a prognosis following stroke have been well-documented in the general stroke population, and in patients after MT in particular." (PMID 38565588, 2024). "Serum SIRT2 levels were also positively correlated with NIH Stroke Score, tumor necrosis factor-α, IL-6 and IL-17." (PMID 39001884, 2024).
Stroke (continued). "In this study, stroke-free individuals carrying the IL-6 GG genotype displayed an 11% higher increase in CIMT compared to individuals with the CC+GC genotypes." (PMID 37838929, 2024). "In this context, inflammatory markers such as neutrophils, lymphocytes, CRP, and IL-6 play an important role in predicting stroke severity as per the NIHSS, disability as per the mRS, poor outcomes according to the BI, and overall mortality." (PMID 38169754, 2024). "We examined the post-stroke inflammatory response in our model and found that the levels of pro-inflammatory cytokines, including interleukin (IL)-1β and IL-6, were significantly increased in the infarcted brain tissues." (PMID 39631782, 2024). "For the first time, our findings revealed that circulating NETs, PAD4, C1q, IL-1β, IL-6 and IL-8 levels peaked at 24 hours after stroke onset, followed by a gradual decline." (PMID 39737165, 2024). "Proinflammatory cytokines such as Il-6 are increased following stroke and correlate with poor stroke outcome." (PMID 39000490, 2024). "Upon analysis with mixed linear regression methods, elevated IL-6, TCC, and MIP-1α at baseline (median of 4 d) were associated with lower MoCA scores by 5–7 points at 3, 18, and 36 months after stroke." (PMID 41542283, 2024). "Reducing serum inflammatory factors (such as high-sensitivity C-reactive protein, tumor necrosis factor-α, interleukin-6) in patients with stroke." (PMID 39211435, 2024). "Clinical data were recorded and compared, including lipid profile, interleukin-6 (IL-6), homocysteine (Hcy), National Institutes of Health Stroke Scale (NIHSS) score, and HNL." (PMID 38233767, 2024). "In stroke, we are straightened by inflammations involving interleukins (especially IL-6 and IL-1) and immune cytokines, and inflammatory factors increase and complicate subsequent tissue regeneration." (PMID 39166055, 2024). "For detail, MPO-DNA, PAD4, C1q, IL-1β, IL-6 and IL-8 reached their peak at 24 hours after stroke onset and show a decreasing trend throughout the acute phase of stroke, while HMGB1 peaked at 48 hours after stroke onset." (PMID 39737165, 2024). "Further longitudinal studies (including cytokine analysis such as IL-6) are warranted to investigate the temporal relationship between sex, inflammation, and depressive symptoms after stroke." (PMID 37848651, 2024). "Nonetheless, a plethora of evidence suggests IL-6 is elevated in stroke and is significantly correlated with lesion size and worse functional outcome." (PMID 38502340, 2024). "It has been reported that post-stroke administration of metyrapone, an inhibitor of glucocorticoid synthesis, decreased the IL-6 level and the infarct size in the ischemic brain." (PMID 39195495, 2024). "After stroke, IL-6 is capable of modulating the function of stromal cells, promoting neuronal damage, and adversely affecting the recovery of neurological function." (PMID 38742047, 2024). "TNF-α, IL-6, IL-1β, and IL-10 were also measured in peripheral blood samples to examine the possible effect of peripheral inflammatory response on the recurrent stroke." (PMID 38216560, 2024). "We know that upregulation of IL-6 on glial cells or neurons in stroke can reflect passive passage and systemic release due to disruption of the blood-brain barrier." (PMID 38169640, 2024). "Experimental studies using mouse models have demonstrated the involvement of IL-6 in the process of neuronal redeath following stroke." (PMID 38742047, 2024). "Increased serum levels of CRP and IL-6 correlate with stroke severity; notably, patients with moderate to severe strokes generally present higher CRP and IL-6 levels." (PMID 38671959, 2024). "The volcano plot indicates significant downregulation of genes already implicated in inflammation and apoptotic cell death following stroke such as Ccr5, Casp8, Icam2, Mmp9, Pecam1, and Il6." (PMID 39000490, 2024).